INS (insulin)
Diseases named in the same sentence as INS in open-access papers (continued):
Sharing a sentence is not in itself a finding about the gene and the disease.
Insulin resistance (continued). "Mice treated 28 days with praliciguat had lower levels of fasting plasma insulin, C-peptide, triglycerides, and HOMA-IR (homeostatic model assessment for insulin resistance) than DIO controls." (PMID 35308230, 2022). "In the case of insulin resistance, FFA mobilization (lipolysis) in adipose tissues is accelerated due to decreased insulin inhibition, leading to higher FFA in plasma." (PMID 36359836, 2022). "The current study demonstrated that MG induced T2D and insulin resistance, and this action was related to the enhancement of FBG and HOMA-IR and decreasing of HOMA-β, QUICKI, and insulin DI." (PMID 35655590, 2022). "Consistently with previously reported data, the elevation of circulating insulin level and lower serum level of IGF-1 indicates that orchiectomy induced insulin resistance." (PMID 35547008, 2022). "To gain more insights into potential alterations in insulin sensitivity, we calculated the HOMA-IR (Homeostatic Model of Insulin Resistance) and the Matsuda insulin sensitivity index." (PMID 35624726, 2022). "The data on the positive correlation between OPG and insulin sensitivity correspond well with the findings that FFA elevation decreases serum OPG, together with inducing insulin resistance." (PMID 35215487, 2022). "In patients, the fasting glucose and insulin were higher, as these PCOS patients developed T2DM and insulin resistance during the course of the disease." (PMID 35455702, 2022). "In this cohort (n = 576), we calculated insulin resistance using the homeostatic model assessment for insulin resistance (HOMA-IR) by taking into account fasting glucose and insulin concentration." (PMID 35057804, 2022). "Both studies recorded improvements in scores in the homeostasis model of assessment of insulin resistance (HOMA-IR) and quantitative insulin sensitivity check (QUICKI) indexes." (PMID 35408987, 2022). "For example, it has been demonstrated that fxr knockout mice had insulin resistance and hyperglycemia; meanwhile, FXR agonist GW4064 administration decreased serum glucose, increased liver glycogen, and improved insulin sensitivity." (PMID 35806234, 2022). "T1DM accounts for about 5–10% of all patients with DM, and it results from pancreatic beta cells dysfunction with reduced insulin secretion, while type 2 DM (T2DM) is related to insulin resistance and accounts for 90–95% of all diabetic patients." (PMID 35562979, 2022). "The interactions among circulating sphingolipids and among other insulin responsive biomolecules such DAG and HMW adiponectin that are apparent in healthy animals are lost in the impaired animals even in advance of insulin resistance onset." (PMID 35705631, 2022). "HOMA insulin resistance index (HOMA-IR) was calculated as [Plasma glucose (GLU, mmol/L)* serum insulin (mIU/L)] / 22.5." (PMID 35443645, 2022). "We have also shown that resistin at the hypothalamic level inhibits insulin signaling as well as that of adiponectin and FGF21, inducing hypothalamic and peripheral insulin resistance." (PMID 36078135, 2022). "It has been shown previously that treatment with pasteurized A. muciniphila resulted in a much lower insulin concentration when compared to the HFD group, resulting in a lower insulin resistance (IR) index." (PMID 35805168, 2022). "Excessive insulin resistance (IR), commonly calculated by two insulin indices: the homeostasis model assessment of insulin resistance (HOMA-IR) and quantitative insulin sensitivity check index (QUICKI), is a contributory factor in the pathogenesis of GDM." (PMID 36714591, 2022). "After a 12-week long intake of Calanus oil, a significant improvement in hepatic IR index, homeostatic model assessment for insulin resistance (HOMA-IR), and fasting insulin levels were observed." (PMID 35454311, 2022). "TNF inhibitors appear to mainly act as insulin-sensitizing agents by attenuating TNF-α-induced insulin resistance, particularly in patients with a high degree of insulin resistance." (PMID 35629988, 2022).
Insulin resistance (continued). "Altogether, these induce insulin resistance by promoting serine-phosphorylation of IRS-1, which impairs insulin signaling and subsequently inhibits glucose uptake by target cells." (PMID 36434695, 2022). "For the first time, after treatment with SG-loaded nanosystem, we employed insulin tolerance tests (ITTs) to measure insulin sensitivity and the homeostatic model assessment (HOMA) to describe insulin resistance." (PMID 35624887, 2022). "And the fasting venous blood samples were collected for determination of blood glucose level, homeostasis model assessment of insulin resistance (HOMA-IR), peptide C, and basal insulin level." (PMID 36060656, 2022). "In Western blotting analysis using N2a cells under insulin resistance, we found that phosphorylation of RAC/Cdc42 was commonly decreased under both insulin-resistant conditions." (PMID 35055191, 2022). "Although obesity and measures of insulin resistance were similar between GDM and non GDM groups, notable highlighted metabolic abnormalities were seen in insulin secretion in the GDM group." (PMID 36295825, 2022). "Studies in vivo have reported that GZFL efficiently reduced fasting blood glucose, fasting insulin level, and insulin resistance index in plasma of PCOS rats with insulin resistance." (PMID 35529925, 2022). "Specifically, insulin resistance in adipocytes induced by TNF-α and IL-6 attenuates the inhibitory effect of insulin on lipolysis and FFA release." (PMID 35406450, 2022). "HFD-CQA mice displayed lower fasting blood glucose, insulin, and HOMA-IR index than HFD-V mice, which further confirmed the improvement of insulin resistance by CQA treatment." (PMID 36517893, 2022). "The pathogenesis of T2DM is primarily characterized by impaired insulin secretion (IIS) and peripheral insulin resistance (IR) (or decreased insulin sensitivity)." (PMID 36497154, 2022). "Indices of insulin sensitivity [homeostasis model assessment for insulin resistance (HOMA-IR) and whole-body insulin sensitivity index (WBISI)] and β-cell function [insulinogenic index (IGI) and disposition index (DI)] were calculated." (PMID 35906625, 2022). "The primary outcomes included fasting blood glucose (FBG), fasting serum insulin (FINS), homeostasis model assessment—insulin resistance (HOMA-IR), and body mass index (BMI)." (PMID 36120465, 2022). "In vivo experiments showed that DEL-1 administration increased the expression of SIRT1 and SERCA2, thereby ameliorating insulin resistance in skeletal muscle of high fat diet (HFD)-fed mice and improving HFD-impaired glucose tolerance and insulin sensitivity." (PMID 36518760, 2022). "The dysfunction of β cells, which are responsible for insulin production and release in the pancreas, is a significant component of GDM pathophysiology and is intensified by insulin resistance." (PMID 36232232, 2022). "Insulin resistance can downregulate PI3K-Akt pathway, which plays an important role in insulin regulation by regulating growth factors, reducing insulin resistance, enhancing glucose transport function, and regulating blood glucose and lipid metabolism." (PMID 36452059, 2022). "Our results demonstrated that maternal stress-exposed offspring had increased plasma insulin levels and insulin resistance (HOMA-IR index), and decreased plasma glucose levels and insulin sensitivity (Matsuda index) in adulthood." (PMID 35869151, 2022). "Homeostasis model assessment of insulin resistance (HOMA-IR), HOMA of insulin sensitivity (HOMA-IS), and triglyceride–glucose index (TyG) were calculated." (PMID 36157456, 2022). "Hepatic insulin resistance was estimated using the HOMA-IR and whole-body insulin sensitivity was estimated using the Matsuda index." (PMID 35893386, 2022). "SIAP2 treatment decreased the fasting insulin level by − 5.25 mg/dL and HOMA-IR, a surrogate marker of insulin resistance, by − 1.33 compared with the placebo group." (PMID 35643872, 2022).
Insulin resistance (continued). "Hyperinsulinemia is a common symptom of T2DM, leading to decreased insulin signaling in the liver and skeletal muscle by increasing the p-s-IRS level, thereby resulting in insulin resistance." (PMID 36699697, 2022). "Blood glucose concentrations were similar in 6 h fasted mice whereas plasma insulin and HOMA-IR were elevated suggesting mild insulin resistance." (PMID 36064109, 2022). "Moreover, HOMA-IR as the index of insulin resistance was also significantly reduced in empagliflozin compared to placebo [adjusted mean difference: − 1.18 (− 1.47; − 0.89), P < 0.001) (patients who used insulin as anti-diabetic therapy were excluded from this analysis)." (PMID 36397128, 2022). "Serine phosphorylation of IRS1 increases with insulin resistance, and serine hyperphosphorylation of IRS1 is thought to be a negative regulator of insulin signal transduction in general." (PMID 36589630, 2022). "Further analysing the insulin resistance and insulin sensitivity in the T2DM rat model, we obtained the fasting serum insulin and fasting blood glucose to compute the HOMA-IR, HOMA-β and QUICKI indexes." (PMID 35336023, 2022). "Overexpressing Ddr2 in 3T3-L1 adipocytes leads to reduction of insulin-stimulated IRS-1 tyrosine phosphorylation and glucose transporter, thereby insulin resistance." (PMID 34645939, 2022). "Homeostatic model assessment (HOMA) is a convenient and economic method to quantify β-cell function of insulin secretion (HOMA-β), insulin resistance (HOMA-IR) and insulin sensitivity (HOMA-IS) with measurement of fasting blood glucose and insulin." (PMID 36045734, 2022). "Regarding the role of insulin resistance in PCOS, we performed GTT and ITT analysis to detected the effect of enoxacin on glucose tolerance and insulin sensitivity." (PMID 36147348, 2022). "IFG is thought to be the result of hepatic insulin resistance, whereas IGT results primarily from reduced peripheral insulin sensitivity." (PMID 35629908, 2022). "This study reveals the crucial role of miR-183-5p in the insulin signaling pathway by targeting IRS-1 and suggests a novel mechanism for hepatic insulin resistance in obesity." (PMID 35328400, 2022). "However, the information of the simple diagnostic OGTT do not allow assessment of insulin resistance, which requires insulin measurement in addition to glucose and takes advantage from possible collection of more blood samples rather than the 60 and 120 min samples only." (PMID 36258194, 2022). "They settled the cross-sectional study with 600 PCOS women who underwent anthropometric measurements and analyses of insulin, fasting blood glucose, total testosterone, SHBG, liver function, lipid accumulation product, and insulin resistance markers." (PMID 35052811, 2022). "T2D increased plasma glucose concentration, glycated hemoglobin level, and insulin resistance, estimated on the HOMA-IR index, and decreased plasma insulin level." (PMID 35457103, 2022). "MS-induced elevations in the serum glucose, insulin levels, and HOMA-IR imply the development of insulin resistance." (PMID 35990819, 2022). "In animal models, TMAO has been shown to induce T2D via increasing fasting insulin levels and insulin resistance (HOMA-IR), aggravating impaired glucose tolerance, inducing adipose tissue inflammation, and obstructing the hepatic insulin signalling pathway." (PMID 35631234, 2022). "They observed that the increased O-GlcNAc modification of IRS-1 and Akt2 reduced the insulin-stimulated phosphorylation of IRS-1 and Akt2, which induced insulin resistance characterized by prominently decreased GLUT4 translocation in adipocytes." (PMID 36005597, 2022). "In contrast, older adults from this cohort showed a negative correlation between glycine status and the Homeostatic Model Assessment for Insulin Resistance (HOMA-IR), a composite score indicating differences in insulin sensitivity." (PMID 35821844, 2022).
Insulin resistance (continued). "DM1 is associated with deficits in insulin production and requires daily administration of insulin, while DM2 results from a decrease in insulin production due to insulin resistance." (PMID 36554003, 2022). "On the other hand, insulin sensitizers, such as myo-inositol (MI) and D-chiroinositol (DCI), can significantly alleviate insulin resistance in PCOS, thereby ameliorating PCOS." (PMID 35747760, 2022). "They had insulin resistance with a higher HOMA-IR value than Chow, and elevated circulating insulin." (PMID 35163991, 2022). "Elevated O-GlcNAcylation also contributed to insulin resistance in adipocytes by modifying IRS-1 and inhibiting its phosphorylation, impairing insulin signaling." (PMID 35527999, 2022). "This insulin resistance is markedly exaggerated in adolescents T1DM, especially in obese ones, leading to defects in both the plasma glucose and lipid-lowering effects of insulin." (PMID 36042901, 2022). "That is why the aim of our study was to investigate the effect of MLD on the insulin resistance parameter (HOMA-IR), HbA1c, C-peptide, insulin, FPG, 2h-PG and the concentration of hsCRP in patients with abnormal body mass index." (PMID 35885034, 2022). "Interestingly, the local genetic covariance we have highlighted between neuropsychiatric disorders and somatic diseases linked to insulin resistance was in most cases in the negative direction at the level of gene sets related to insulin signalling, except for AN and ADHD." (PMID 35165256, 2022). "First, uric acid induces insulin resistance by inhibiting intrahepatic IRS1 and Akt insulin signaling, which promotes the liver fat accumulation." (PMID 36079844, 2022). "This propensity is especially higher when there is an increase in insulin synthesis demand, which occurs during the progression to T2DM, a long period of time with a characteristic insulin resistance and an mTORC1 hyperactivity." (PMID 36465657, 2022). "However, most previous studies estimated that IL-1β secreted from macrophages mediates macrophage-adipocyte cross-talk and impairs insulin signaling in human primary adipocytes, which might overlook the effect of pro-inflammatory cytokines released from preadipocytes on insulin resistance." (PMID 36234919, 2022). "Besides their involvement in tissue inflammation and the development of insulin resistance in peripheral tissues, free fatty acids (FFAs), particularly long-chain (Lc-FFAs) and saturated FFAs, might contribute to abnormal insulin response at several stages of their metabolism." (PMID 35884932, 2022). "The virus is responsible for peripheral and hepatic insulin resistance due to increased TNF-α secretion and other pro-inflammatory cytokines that interfere in post-receptor insulin signaling pathways." (PMID 35315984, 2022). "In insulin target tissues such as liver and fat, the upregulation of GLUT4 and the activation of AMPK facilitates glucose utilization to ameliorate insulin resistance." (PMID 35495935, 2022). "Because the insulin signaling transduction pathway plays a critical role in insulin resistance, we further elucidated the effect of TLB on the insulin signaling transduction pathway." (PMID 35153796, 2022). "Although fasting levels of GCGN are positively correlated with insulin resistance and IHL, increasing prandial GCGN secretion by HPD improves IHL, insulin sensitivity, fasting glucose, and circulating free saturated fatty acids." (PMID 35662921, 2022). "Like type 2 diabetes, peripheral insulin resistance and decreased insulin secretion play roles in the GDM pathophysiology; however, the exact reasons for insulin dysfunction in GDM remain poorly understood." (PMID 35503790, 2022). "Plasma insulin and HOMA-IR, a marker of insulin resistance, were significantly increased in rats after they had consumed the HSD for 5 weeks; there were no changes in fasting blood glucose levels." (PMID 36297523, 2022).
Insulin resistance (continued). "Clinical studies have demonstrated the link between insulin resistance and T2DM, and insulin-sensitizing managements such as dietary control and exercises are proved effective in dealing with metabolic disorders." (PMID 36352450, 2022). "The results of this study found that the addition of AAP significantly inhibited the increase in the blood glucose and insulin levels and decreased HOMA-IR index, indicating that AAP had positive regulatory effects on insulin resistance." (PMID 35407029, 2022). "Although the causes and mechanisms leading to insulin resistance have not yet been clearly understood, the poor insulin sensitivity may result from the blockade of the insulin signaling cascade in insulin target tissues such as the skeletal muscle, liver, and white adipose tissue in MetS subjects." (PMID 36358481, 2022). "Since the homeostasis model assessment of insulin resistance (HOMA-IR) is a simple and useful method for evaluating insulin sensitivity, the HOMA-IR was employed in the current study." (PMID 35893262, 2022). "Ablation of NK cells prevents the differentiation of M1 macrophages, reduces inflammation, and restores insulin sensitivity, while expansion of NK cells exacerbates DIO-induced inflammation and insulin resistance." (PMID 35574038, 2022). "Insulin resistance-related phenotypes, including HOMA-IR, fasting insulin, HbA1c, and fasting glucose, were increased from baseline to follow-up (p<0.05)." (PMID 35585555, 2022). "Both levels of serum glucose and insulin were significantly higher in HFD-fed mice, which meant the HFD-fed mice developed insulin resistance." (PMID 36425072, 2022). "Indeed, a decreased sensitivity to the normal vascular actions of insulin impedes nitric oxide (NO) production and bioability due to oxidative burden, thus playing an additional important role in the development of endothelial dysfunction in states of insulin resistance." (PMID 36289641, 2022). "Several studies have shown that vitamin D supplements reduce insulin resistance in T2DM and improve insulin secretion and sensitivity." (PMID 35345711, 2022). "Insulin sensitivity was enhanced following ADSC infusion, as indicated by improvements in IPITT, homeostatic model assessment of insulin resistance (HOMA-IR), and GIR, which were further improved in the pre-ADSC group." (PMID 35986406, 2022). "Myeloid lineage-specific BRD4 knockout mice fed a high-fat diet display reduced local and systemic inflammation and improved insulin sensitivity, while overexpression of BRD2 in white adipose tissues from wild-type mice induces insulin resistance." (PMID 36015180, 2022). "In WT, HFHSD gained weight and increased insulin resistance, which increased blood glucose, whereas, in SOD1−/−, blood glucose was thought to increase due to decreased insulin secretion." (PMID 35883894, 2022). "Non-obese patients with extreme insulin resistance due to pathogenic variants in the insulin receptor (Rabson-Mendenhall syndrome) and high circulating insulin levels have been found to have thyromegaly, supporting insulin as a mediator of the link between common obesity and thyroid proliferation." (PMID 35158824, 2022). "Insulin sensitivity (HOMA2-%S) and insulin resistance (HOMA2-IR) were significantly different between the timepoints." (PMID 35160113, 2022). "We further evaluated glucose homeostasis by calculating the homeostasis model assessment of insulin resistance (HOMA-IR) and by performing glucose and insulin tolerance tests (GTTs and ITTs)." (PMID 35743232, 2022). "Migraine patients had significantly higher waist circumference, higher mean values of serum insulin, HOMA-IR and higher frequency of insulin resistance and metabolic syndrome than the control group (P-value = 0.005, 0.049, 0.01, 0.012, 0.024, respectively)." (PMID 36368970, 2022).